ROCK1 (Rho associated coiled-coil containing protein kinase 1)
Description:
Protein kinase which is a key regulator of the actin cytoskeleton and cell polarity. Involved in regulation of smooth muscle contraction, actin cytoskeleton organization, stress fiber and focal adhesion formation, neurite retraction, cell adhesion and motility via phosphorylation of DAPK3, GFAP, LIMK1, LIMK2, MYL9/MLC2, TPPP, PFN1 and PPP1R12A. Phosphorylates FHOD1 and acts synergistically with it to promote SRC-dependent non-apoptotic plasma membrane blebbing. Phosphorylates JIP3 and regulates the recruitment of JNK to JIP3 upon UVB-induced stress. Acts as a suppressor of inflammatory cell migration by regulating PTEN phosphorylation and stability (By similarity). Acts as a negative regulator of VEGF-induced angiogenic endothelial cell activation. Required for centrosome positioning and centrosome-dependent exit from mitosis (By similarity). Plays a role in terminal erythroid differentiation. Inhibits podocyte motility via regulation of actin cytoskeletal dynamics and phosphorylation of CFL1 (By similarity). Promotes keratinocyte terminal differentiation. Involved in osteoblast compaction through the fibronectin fibrillogenesis cell-mediated matrix assembly process, essential for osteoblast mineralization (By similarity). May regulate closure of the eyelids and ventral body wall by inducing the assembly of actomyosin bundles (By similarity).
Synonyms: ROCK-I; p160ROCK
Tractability: Small molecule: an approved drug acts on it; a structure with a bound ligand is known; a high-quality ligand is known; it has a high-quality binding pocket; it belongs to a druggable protein family. Antibody: UniProt places it where antibodies can reach, with high confidence; its Gene Ontology location is reachable by antibodies, with high confidence. PROTAC: ubiquitination databases record sites on it; its protein half-life has been measured; a small molecule that binds it is known.
Target class: AGC protein kinase DMPK family; Enzyme; Kinase; Protein Kinase; AGC protein kinase ROCK subfamily; AGC protein kinase group
Chemical probes: BAY-549 (high quality), CHEMBL575741, PD134236, PD134237, PD134238, PD134239, PD134240, PD134241, PD134242, PD134243
Safety:
Unwanted effects reported when the protein is acted on. In parentheses: how it was acted on, where the effect was seen, and who reports it.
Anxiety (inhibition; central nervous system; source: Brennan et al. (2024))
cardiac dysfunction (inhibition; cardiovascular; source: Brennan et al. (2024))
conjunctival hyperaemia (inhibition; ocular; source: Brennan et al. (2024))
cytopenia (inhibition; blood/bone marrow; source: Brennan et al. (2024))
GI inflammation (inhibition; gastrointestinal; source: Brennan et al. (2024))
hypertrophic cardiomyopathy (inhibition; cardiovascular; source: Brennan et al. (2024))
hypotension (inhibition; cardiovascular; source: Brennan et al. (2024))
lymphatic disorder (inhibition; lymph; source: Brennan et al. (2024))
pulmonary hypertension (inhibition; respiratory; source: Brennan et al. (2024))
cardiac arrhythmia (cardiovascular system; source: Lamore et al. (2017))
heart disease (cardiovascular system; source: Force et al. (2011))
Gene: Protein-coding gene on chromosome 18 (20,944,612 to 21,111,813, reverse strand). Ensembl gene ENSG00000067900.
Subcellular location: Cytoplasm; Cytoplasm, cytoskeleton, microtubule organizing center, centrosome, centriole; Golgi apparatus membrane; Cell projection, bleb; Cytoplasm, cytoskeleton; Cell membrane; Cell projection, lamellipodium; Cell projection, ruffle
Pathways (Reactome):
Signal Transduction: G alpha (12/13) signalling events; RHO GTPases Activate ROCKs; RHOA GTPase cycle; RHOB GTPase cycle; RHOBTB1 GTPase cycle; RHOC GTPase cycle; RHOH GTPase cycle; RND3 GTPase cycle; VEGFA-VEGFR2 Pathway
Developmental Biology: EPHA-mediated growth cone collapse; EPHB-mediated forward signaling; Sema4D induced cell migration and growth-cone collapse
Disease: Potential therapeutics for SARS
Immune System: Neutrophil degranulation
Programmed Cell Death: Apoptotic cleavage of cellular proteins
Gene Ontology:
Molecular function: protein binding; protein serine kinase activity; protein serine/threonine kinase activity; Rho-dependent protein serine/threonine kinase activity; tau protein binding; tau-protein kinase activity; ATP binding; protein kinase activity; small GTPase binding
Biological process: intracellular signal transduction; leukocyte cell-cell adhesion; leukocyte migration; leukocyte tethering or rolling; membrane to membrane docking; negative regulation of amyloid precursor protein catabolic process; negative regulation of amyloid-beta formation; negative regulation of angiogenesis; negative regulation of bicellular tight junction assembly; negative regulation of protein binding; neuron projection arborization; neuron projection development; peptidyl-serine phosphorylation; positive regulation of amyloid-beta clearance; positive regulation of autophagy; positive regulation of cardiac muscle hypertrophy; positive regulation of connective tissue replacement; positive regulation of gene expression; positive regulation of MAPK cascade; protein localization to plasma membrane; regulation of actin cytoskeleton organization; regulation of angiotensin-activated signaling pathway; regulation of cell migration; regulation of establishment of endothelial barrier; regulation of keratinocyte differentiation; and 31 more
Cellular component: cytoplasm; Golgi membrane; cytoplasmic stress granule; cytoskeleton; cytosol; extracellular region; lamellipodium; plasma membrane; ruffle; secretory granule lumen; bleb; centriole; Schaffer collateral - CA1 synapse
Genetic constraint (gnomAD): Loss-of-function variants: 19 observed, 95.27 expected, observed/expected ratio (o/e) 0.2, 90% interval 0.14 to 0.29. The upper end of that interval is the gene's LOEUF score, 0.29, which puts it in group 1 of 6, group 1 being the genes least tolerant of losing a copy. Missense variants: 526 observed, 939.61 expected, observed/expected ratio (o/e) 0.56, 90% interval 0.52 to 0.6. Synonymous variants: 270 observed, 313.53 expected, observed/expected ratio (o/e) 0.86, 90% interval 0.78 to 0.95.
Homologues: Orthologues: chimpanzee ROCK1 (99% identical), macaque ROCK1 (99% identical), pig ROCK1 (98% identical), rabbit ROCK1 (98% identical), guinea pig ROCK1 (97% identical), mouse Rock1 (97% identical), rat Rock1 (96% identical), tropical clawed frog rock1 (81% identical), zebrafish rock1 (76% identical), Drosophila melanogaster Rok (44% identical), Caenorhabditis elegans let-502 (32% identical). Paralogues in human: ROCK2 (66% identical), CIT (28% identical), CDC42BPA (26% identical), CDC42BPB (26% identical), CDC42BPG (21% identical).
Diseases named in the same sentence as ROCK1 in open-access papers:
ROCK1 is named in the same sentence as 253 diseases in open-access papers, as found by Europe PMC text mining. Sharing a sentence is not in itself a finding about the gene and the disease. The quoted sentences say what the papers report.
osteosarcoma (72 papers, 2014 to 2026). A usually aggressive malignant bone-forming mesenchymal neoplasm, predominantly affecting adolescents and young adults. "Rho-associated kinase 1 (ROCK1) has been identified as a target gene of miR-214 in osteosarcoma cells." (PMID 34399695, 2021). "Accordingly, miR-145 has been described to upregulate myocardin during smooth muscle differentiation and proliferation, while the same miRNA downregulates Rho-associated protein kinase-1 (ROCK1) in cases of osteosarcoma." (PMID 32731349, 2020). "Previously, we reported that Rho associated coiled-coil containing protein kinase 1 (ROCK1), a metastatic-related gene was negatively regulated by microRNA-335-5p (miR-335-5p) and work as an oncogene in osteosarcoma." (PMID 29753317, 2018). "For example, the SNHG1 lncRNA sequestered miR-302/372/373/520 and consequently activated TGFBR2 and RAB11A in invasive pituitary tumors, while DANCR acted as a decoy for miR-335-5p and miR-1972, thus promoting ROCK1-associated proliferation and metastasis in osteosarcomas." (PMID 30774556, 2019). "Up-regulation of miR-144 could suppress osteosarcoma cells migration and invasion by targeting regulation of rho associated coiled-coil kinase 1 (ROCK1) and rho associated coiled-coil kinase 2 (ROCK2)." (PMID 28938647, 2017). "But the function and mechanism it works on in osteosarcoma proliferation and metastasis mediated by Rho associated coiled-coil containing protein kinase 1 (ROCK1) and Rho associated coiled-coil containing protein kinase 2 (ROCK2) remain unclear." (PMID 28938647, 2017). "Our data offer the convincing evidence for the first time that the combined miR-340 downregulation and ROCK1 upregulation may be linked to tumor progression and adverse prognosis in pediatric osteosarcoma." (PMID 24398981, 2014). "In addition, the association between combined expression status of miR-340/ROCK1 and the prognosis of patients with osteosarcomas was also tested by the Kaplan-Meier method." (PMID 24398981, 2014). "Our data offer convincing evidence, for the first time, that the combined miR-340 downregulation and ROCK1 upregulation may be linked to tumor progression and adverse prognosis in pediatric osteosarcoma." (PMID 24398981, 2014). "On this basis, we hypothesized that the combined dysregulation of miR-340 and its target mRNA ROCK1 might be associated with tumor progression and prognosis in patients with osteosarcoma." (PMID 24398981, 2014). "More importantly, we found that the combined miR-340 and ROCK1 mRNA expression profiling may be more significantly associated with tumor aggressiveness of pediatric osteosarcoma than the abnormal expression of miR-340 or ROCK1 mRNA alone." (PMID 24398981, 2014). "Particularly ROCK1 appears to be relevant in many human cancer types, as immunohistochemistry studies reported associations between adverse tumor features and increased ROCK1 protein levels in breast, colorectal, and gastric cancers as well as in osteosarcomas." (PMID 31557128, 2019). "DANCR can also function as a ceRNA in osteosarcoma by binding to miR-335-5p and miR-1972, which promote ROCK1-mediated proliferation and metastasis." (PMID 41602364, 2026). "The downregulation of miR-335 in Osteosarcoma cells leads to unchecked ROCK1 expression, enhancing tumor aggressiveness and metastatic potential, particularly to the lungs." (PMID 40429954, 2025). "Conversely, the restoration of miR-335 expression has been shown to significantly suppress Osteosarcoma cell invasion and metastasis by inhibiting ROCK1-mediated cytoskeletal rearrangements and cell motility." (PMID 40429954, 2025). "In Osteosarcoma, ROCK1 is frequently upregulated, contributing to increased tumor cell migration, invasion and EMT." (PMID 40429954, 2025). "For example, MIR145 mediates myocardin gene upregulation during muscle differentiation, while the same miRNA induces ROCK1 downregulation in osteosarcoma." (PMID 38413914, 2024).
osteosarcoma (continued). "The Rho-associated coiled-coil containing protein kinase 1 (ROCK1) was reported to be a proliferation- and metastasis-related gene in various cancers including osteosarcoma." (PMID 37197432, 2023). "Now, they have identified a novel circRNA called circROCK1-E3/E4 derived from ROCK1, which acts as a tumor suppressor in osteosarcoma." (PMID 35879346, 2022). "The interactions between miRNAs and ROCK1 have been mostly assessed in osteosarcoma cells among other cancers." (PMID 36177350, 2022). "miR-1908 can not only inhibit the development of osteosarcoma by targeting ROCK1, but also activate the PI3K/AKT signaling pathway to promote the development of osteosarcoma." (PMID 35463352, 2022). "The LncRNA AFAP1-AS1 promotes tumorigenesis and epithelial-mesenchymal transition of osteosarcoma through the RhoC/ROCK1/p38MAPK/Twist1 signaling pathway." (PMID 35179516, 2022). "In the present study, we concentrated on investigating the expression and function of hsa_circ_0108024, a circular RNA derived from exons 3 and 4 of the ROCK1 gene, in osteosarcoma." (PMID 35879346, 2022). "The lncRNA DANCR has been documented to function by decoying miR-335-5p and miR-1972 in osteosarcoma and to facilitate ROCK1-mediated proliferation and metastasis." (PMID 35755302, 2022). "We provided evidence that circROCK1-E3/E4, which is produced from exons 3 and 4 of ROCK1 precursor mRNA, was downregulated in osteosarcoma." (PMID 35879346, 2022). "Yong Wang at Zhejiang University, China, and co-workers had already demonstrated that the ROCK1 gene plays critical roles in osteosarcoma progression." (PMID 35879346, 2022). "Emerging evidence has revealed that miR-335 overexpression retarded invasion and migration of osteosarcoma cells via repressing ROCK1 and SNIP1 expression." (PMID 35252166, 2022). "MALAT1 promoted proliferation and metastasis via sponging miR-144-3p and blocking ROCK1/ROCK2 axis in osteosarcoma cells." (PMID 35252166, 2022). "But on the contrary, another study found that miR-1908-5p can target ROCK1, thereby inhibiting the proliferation of osteosarcoma cells (HOS, MG293, G63, SAOS2, and U2OS)." (PMID 35463352, 2022). "ROCK1 overexpression is reported in many different types of cancer, including glioblastoma, melanoma, osteosarcoma, prostate cancer and HCC." (PMID 35287604, 2022). "And it was demonstrated in osteosarcoma that lncRNA HOXA11-AS can up-regulate ROCK1 gene expression by sponging miR-124-3p." (PMID 34715856, 2021). "The targeting relationship between miR-214 and ROCK1 has been investigated in osteosarcoma and hepatocellular carcinoma cells." (PMID 34399695, 2021). "DANCR promotes progressive osteosarcoma by functioning as a ceRNA and sponging miR-335-5p and miR-1972, regulating ROCK1 expression." (PMID 35096852, 2021). "LncRNA CCHE1 siRNA silencing inhibited, while ROCK1 overexpression promoted osteosarcoma cell invasion and migration." (PMID 32660450, 2020). "Consistently, our study also observed significantly upregulated plasma ROCK1 in osteosarcoma patients than in healthy controls on the day of discharger." (PMID 32660450, 2020). "DANCR promotes ROCK1-mediated proliferation and metastasis via crosstalk with miR-335-5p and miR-1972 in osteosarcoma." (PMID 32019566, 2020). "For instance, the lncRNA DANCR, has been described to behave as a ceRNA for miR-335-5p and miR-1972, thereby enhancing ROCK1-mediated osteosarcoma pathogenesis." (PMID 33023613, 2020). "For example, miR-101 suppresses cell proliferation and facilitates cell apoptosis by inhibiting mTOR in Saos-2 cells, promotes Bcl2-regulated apoptosis by RLIP76 in prostate cancer cells, represses tumour growth and migration by ROCK1 in osteosarcoma cells." (PMID 33072314, 2020). "In our study, AFAP1-AS1 knockdown downregulated the expression levels of RhoC, ROCK1, phosphorylated p38MAPK, and Twist1 in osteosarcoma cells." (PMID 31443665, 2019).
osteosarcoma (continued). "AFAP1-AS1 is overexpressed in osteosarcoma and plays an oncogenic role in osteosarcoma through RhoC/ROCK1/p38MAPK/Twist1 signaling pathway, in which RhoC acts as the interaction target of AFAP1-AS1." (PMID 31443665, 2019). "Our results indicated that knockdown of AFAP1-AS1 led to decreased expression levels of RhoC and ROCK1 in osteosarcoma cell lines." (PMID 31443665, 2019). "This study demonstrates lncRNA AFAP1-AS1 is overexpressed in osteosarcoma and plays an oncogenic role in osteosarcoma through RhoC/ROCK1/p38MAPK/Twist1 signaling pathway, in which RhoC acts as the interaction target of AFAP1-AS1." (PMID 31443665, 2019). "The ceRNA network which are comprised by DNACR, miR-335-5p/miR-1972 and ROCK1 is a hidden corner of iceberg in osteosarcoma." (PMID 29753317, 2018). "Functional experiments illustrated that a depression of DANCR suppressed ROCK1-mediated proliferation and metastasis in osteosarcoma cells." (PMID 29753317, 2018). "As the first encouraging result, we verified that DANCR did promote osteosarcoma cells’ proliferation and metastasis via up-regulation of ROCK1." (PMID 29753317, 2018). "According to our and other previous researches, ROCK1 was closely related to osteosarcoma cells’ proliferation and migration/invasion." (PMID 29753317, 2018). "In our previous studies, we found that miR-335-5p suppressed osteosarcoma cells’ metastatic ability via targeting its downstream gene ROCK1." (PMID 29753317, 2018). "DANCR competitively binds to miR-335-5p and miR-1972 to regulate the expression of ROCK1, thus promoting the malignant biological behaviours of osteosarcoma." (PMID 30419948, 2018). "We firstly demonstrated that ROCK1 was elevated in osteosarcoma tissue specimens and in osteosarcoma cell lines." (PMID 29753317, 2018). "LncRNA DANCR work as an oncogene and promoted ROCK1-mediated proliferation and metastasis through acting as a competing endogenous RNA (ceRNA) in osteosarcoma." (PMID 29753317, 2018). "Inhibition of MALAT1 decreased metastasis and proliferation by regulation of ROCK1/ROCK2 via ceRNA of miR-144-3p in osteosarcoma cells in vitro." (PMID 28938647, 2017). "All these findings confirmed that up-regulation of MALAT1 promoted pulmonary metastasis of osteosarcoma via the miR-144-3p/ROCK1/ROCK2 pathway in vivo." (PMID 28938647, 2017). "In brief, all the data above confirmed that MALAT1 promoted proliferation/metastasis by promoting ROCK1/ROCK2 via a ceRNA of miR-144-3p in osteosarcoma cells MNNG/HOS." (PMID 28938647, 2017). "Recently, miR-340 was reported to directly target two important oncogenes, SKP2 and ROCK1, respectively in lung cancer and in osteosarcoma." (PMID 26799668, 2016). "Multivariate analysis further confirmed that miR-340-low/ROCK1-high expression was an independent prognostic factor of unfavorable survival in pediatric osteosarcoma (for overall survival: p = 0.006, for progression-free survival: p = 0.008)." (PMID 24398981, 2014). "At present, little research has focused on the prognostic values of miR-340 and ROCK1 in osteosarcoma." (PMID 24398981, 2014). "As determined by Spearman’s correlation, the downregulation of miR-340 was negatively correlated with the upregulation of ROCK1 mRNA in osteosarcoma tissues (r = −0.78, p = 0.001)." (PMID 24398981, 2014). "The downregulation of miR-340 was negatively correlated with the upregulation of ROCK1 mRNA in osteosarcoma tissues (r = −0.78, p = 0.001)." (PMID 24398981, 2014). "We also evaluated the clinical significance of miR-340 and ROCK1 dysregulation in pediatric osteosarcomas." (PMID 24398981, 2014). "We only found one other study investigating the effect of ROCK1 protein expression in osteosarcoma samples on patient survival." (PMID 24504141, 2014). "In situ hybridization and immunohistochemistry analysis respectively showed that the positive stainings of miR-340 and ROCK1 protein were both localized in cytoplasm of tumor cells in osteosarcoma tissues." (PMID 24398981, 2014).